BRCA1 (BRCA1 DNA repair associated)
Diseases named in the same sentence as BRCA1 in open-access papers (continued):
Sharing a sentence is not in itself a finding about the gene and the disease.
ovarian carcinoma (continued). "A substantial challenge for ovarian cancer cells in the peritoneum is caused by hypoxia calling for metabolic adaptation Hypoxia has been described to induce the down-regulation of BRCA1 expression resulting in an impairment of cell cycle checkpoint control and DNA repair mechanisms." (PMID 32098278, 2020). "However, it is higher than reported in a large international prospective study of clinically ascertained carriers of a BRCA1 pathogenic variant, with median age at diagnosis of breast and ovarian cancer of 44 and 54 years, respectively." (PMID 32203205, 2020). "Therefore, PARP1 is reportedly overexpressed in multiple cancers including those involving BRCA1/2 mutation, neuroblastoma, ovarian cancer, human papilloma virus-infected oropharyngeal carcinoma, Ewing’s sarcoma, and colon cancer." (PMID 33324554, 2020). "Even though the general population lifetime risk of ovarian cancer is only approximately 1.4%, individuals at high-risk of developing the disease due to harboring a germline BRCA1 and BRCA2 mutation have an average cumulative risk of between 40% to 75% and 11% to 34%, respectively." (PMID 32856862, 2020). "In addition to the known high-penetrance pathogenic variants of BRCA1/2, mutations in other intermediate or low-penetrant genes can increase the risk of breast and/or ovarian cancer." (PMID 32733558, 2020). "Furthermore, the lifetime risk for ovarian cancers is about 39–63% in BRCA1 mutation carriers and 11–27% in BRCA2 mutation carriers." (PMID 33198203, 2020). "In line with this, it is possible that the BRCA1 c.5407-25T>A variant is associated with an increased risk of breast and ovarian cancer, but the magnitude of risk may be lower than for truncating pathogenic BRCA1 variants." (PMID 32203205, 2020). "However, a BRCA1/2 mutation or homologous recombination deficiency are the only biomarkers so far that are clinically applicable for ovarian cancer patients’ selection for targeted therapies." (PMID 32272732, 2020). "Oral contraception leads to a risk reduction of ovarian cancer also in BRCA1/2 mutation carriers." (PMID 32140806, 2020). "BRCA1, a tumor suppressor gene implicated in breast and ovarian cancers, is expressed by endothelial cells and can improve endothelial dysfunction, which may provide a protective role in neurological diseases." (PMID 32381096, 2020). "Identification of invasive lesions in the fimbriae of fallopian tubes from the prophylactic salpingo-oophorectomies of women at high risk of developing ovarian cancer due to germline mutations of BRCA1 and BRCA2 supported this hypothesis." (PMID 33488950, 2020). "Since most studies have limited their observations of BRCA1/2 only in breast and ovarian cancer, the potential relationship of BRCA1/2 pathogenic variants with other cancer types might be underestimated." (PMID 32879886, 2020). "Additionally, there have been several reports analyzing the survival benefit of BRCA1/2 mutations in patients with ovarian cancer." (PMID 32736562, 2020). "The next most significant signature exposure was CN-Sig-3, characterised by evenly distributed chromosome breaks and diploid-to-single copy changes (i.e., loss of heterozygosity), which in ovarian carcinoma was associated with defective homologous recombination and somatic/germline BRCA1/2 mutation." (PMID 32366847, 2020). "Research investigating the biological functions of the proteins encoded by BRCA1/2 have dominated the field since they were identified with speculated critical roles in the analysis of families at high risk from breast and ovarian cancer." (PMID 32638521, 2020). "In a large prospective study of BRCA carriers ascertained through family clinics, the cumulative risk, by age 80, of ovarian cancer in women with pathogenic variants in BRCA1 and BRCA2 was estimated to be 44% (95% confidence interval (CI), 36–53%) and 17% (95% CI, 11–25%), respectively." (PMID 33086730, 2020).
ovarian carcinoma (continued). "Thirdly, that any effect is limited to a subset of BRCA variants (e.g., the Ovarian Cancer Cluster Region which is associated with a much higher relative risk of ovarian cancer than other variants in BRCA1 or BRCA2) and that the variant profile differs in different cohorts." (PMID 31610093, 2020). "BRCA1/2 mutations have been identified in approximately 10–15% of ovarian cancers." (PMID 33015058, 2020). "Several studies have shown that loss-of-function mutation of canonical HR factors – such as breast cancer type 1 and 2 (BRCA1/2) susceptibility proteins that are commonly associated with breast and ovarian cancer – promotes PARP1 hyperactivation in fast replicating cancer cells." (PMID 32295316, 2020). "The BRCA1 gene encodes a nuclear phosphoprotein that plays a role in maintaining genomic stability, and germline mutations within this gene have been highly associated with breast and ovarian cancers." (PMID 33062421, 2020). "About 23% of ovarian cancer cases present a familiar inheritance pattern and are defined as hereditary neoplasms; among them, 65–85% are caused by mutations in BRCA1 and BRCA2 genes, involved in the double-strand DNA breaks (DSBs) repair pathway, that cause 54% of OC lifetime risk increase." (PMID 32512900, 2020). "We also suggested new candidate upregulated or downregulated miRNAs, whose expression were affected by BRCA1 mutation in ovarian cancer development, might be used as a biomarker." (PMID 32854743, 2020). "We speculated that the BRCA1 (3326A>T) mutation may be a susceptibility gene for ovarian cancer in this family." (PMID 32356124, 2020). "However, increased surveillance and prophylactic surgery (mastectomy and salpingo-oophorectomy) can greatly reduce the risk of breast and ovarian cancer in women carrying a BRCA1 or BRCA2 mutation." (PMID 32376921, 2020). "Women with a family history of breast and ovarian cancer have been found to opt for risk reduction surgery, e.g., among BRCA1 and BRCA2 mutation carriers, the majority underwent risk-reducing surgery (salpingo-oophorectomy) after their risk was communicated to them." (PMID 33260928, 2020). "Thus, most studies have focused on cell killing in breast and ovarian cancer cell lines, which are more often associated with a lack wild type BRCA1/2." (PMID 32180937, 2020). "Secondly, only the detection of BRCA1/2 gene mutation was selected in the ovarian cancer family to speculate on the type of gene mutation that may be caused by the family." (PMID 32356124, 2020). "Besides mutations, BRCA1 is silenced through promoter hypermethylation in some breast or ovarian cancers, causing diminished BRCA1 expression level similar to the BRCA1 status in Brca1−/− mice." (PMID 32139898, 2020). "Although only 10–20% of ovarian cancers have germline BRCA1/2 mutations, up to 51% of high-grade serous OC tumor cells contain either a genetic or epigenetic inactivation of BRCA1/2, making both treatment combinations an attractive strategy for recurrent BRCA1/2 mutant OC." (PMID 32098452, 2020). "Germline mutations in BRCA1/2 significantly contribute to hereditary breast and/or ovarian cancer." (PMID 31724318, 2020). "Furthermore, identification of neo-epitopes by circulating T cells was significantly enhanced in patients harboring BRCA1/2-mutated ovarian carcinomas." (PMID 32455819, 2020). "However, somatic and germline mutations and expression loss of BRCA1/2 are sufficiently common in ovarian cancer to warrant assessment for the prediction of treatment benefit in clinical trials of PARPis." (PMID 32211327, 2020). "NJ Birkbak and his colleagues provided evidence to suggest that tumor mutation burden analysis could forecast the outcome in ovarian cancer with BRCA1 or BRCA2 mutations." (PMID 33747898, 2020). "Another example includes BRCA1/2 variants as predictive markers in ovarian cancer." (PMID 31553104, 2020).
ovarian carcinoma (continued). "One of the most dramatic examples of success in this area has been the use of poly-ADP-ribose polymerase (PARP) inhibitors in the treatment of patients with tumours that harbour inactivating mutations in the breast and ovarian cancer susceptibility genes, BRCA1 and BRCA2." (PMID 32183301, 2020). "In addition, in Europe, these guidelines include a search for BRCA1/2 tumor mutations because they are European Medicines Agency-approved targets for treatment with olaparib for ovarian cancer patients with platinum-sensitive relapse." (PMID 31357515, 2019). "The safety of this combination was also investigated in a phase I/II clinical trial in the setting of recurrent ovarian cancer with BRCA1/2 wild-type or unknown mutational status (NCT01690598)." (PMID 31374917, 2019). "Mutations in BRCA1 results in high risk of breast and ovarian cancers." (PMID 31551083, 2019). "Here we have identified a key mechanism by which ZC3H18 regulates the BRCA1 promoter by showing that ZC3H18’s ability to bind directly to the BRCA1 promoter and regulate the association of E2F family members is a major driver of BRCA1 expression in ovarian cancer." (PMID 31604914, 2019). "The mechanism of RM and DOX synergy may be reminiscent of the synthetic lethality in HR-defective breast and ovarian cancer (with BRCA1/2 mutations) treated with PARP inhibitors." (PMID 31527453, 2019). "BRCA1 mutations account for a significant proportion of familial breast and ovarian cancers." (PMID 30006610, 2019). "BRCA1/2 germline mutations are the most common predisposing factors for ovarian cancer development." (PMID 30972954, 2019). "BRCA1 mutations are in close association with hereditary breast and ovarian cancers [-]." (PMID 31998812, 2019). "Notably, ovarian cancer tissue methylation for the BRCA1 promoter, similar to germline BRCA1 mutation status, was associated with the high-grade serous cancer subtype and young age at diagnosis." (PMID 31225507, 2019). "Similarly, in a BRCA1-deficient ovarian cancer model, PARPi led to activation of STING pathway and the therapeutic efficacy was improved with PD-1 blockade." (PMID 31835379, 2019). "Further investigation of the relationship between lymph node metastasis and BRCA1/2 mutation status in ovarian cancer might provide more information for patient stratification." (PMID 30972954, 2019). "The classic demonstration of synthetic lethality is the role of poly(ADP-ribose) polymerase inhibitors (PARPi) in cancers in which homologous recombination DNA repair (HRR) is defective (HRD), particularly in breast and ovarian cancers associated with germline BRCA1 and BRCA2 mutations." (PMID 30871186, 2019). "germline BRCA1 or mutations in families with ovarian cancer only are commonly located in the Ovarian Cancer Cluster Regions when compared to families with both breast and ovarian cancer (P = 0.001, and P = 0.020, respectively)." (PMID 30821131, 2019). "Finally, four patients affected from ovarian cancer carried BRCA1 PVs, while a woman was positive for a deleterious variant in BRCA2 gene." (PMID 31336956, 2019). "Germline mutations in BRCA1 or BRCA2 gene confer a high risk of developing ovarian cancer." (PMID 31064392, 2019). "Height and body mass index (BMI) are associated with higher ovarian cancer risk in the general population, but whether such associations exist among BRCA1/2 mutation carriers is unknown." (PMID 31213659, 2019). "Additionally, it has been reported that homozygosity for the A alleles in miR-SNPs rs12516 and rs8176318, located in the 3′UTR of BRCA1, has a significant association (p = 0.007) with familial breast and ovarian cancer in a Thai cohort." (PMID 30897768, 2019). "Furthermore, another important hallmark of BRCA1/2-associated ovarian cancers is sensitivity to poly(ADP-ribose) polymerase inhibitors (PARPi)." (PMID 30940100, 2019).
ovarian carcinoma (continued). "In addition, reduced BRCA1 is associated with sporadic cancers in these tissues; loss of BRCA1 function has been implicated in the development of breast and ovarian cancer." (PMID 30006610, 2019). "Recently, results of the ENGAGE study demonstrated that an oncologist-led testing process for mutated BRCA1 or 2 genes is feasible in ovarian cancer; the oncology-led testing pathway reported was associated with high levels of acceptance and satisfaction among patients with ovarian cancer." (PMID 31357515, 2019). "These ovarian cancer patients carrying BRCA1/2 mutations could benefit from PARP inhibitors for targeted treatment." (PMID 30972954, 2019). "The cumulative ovarian cancer risk to age 80 years was 44% for BRCA1 and 17% for BRCA2 carriers." (PMID 30915162, 2019). "In summary, our study suggests that higher BMI may be causally associated with ovarian cancer risk in BRCA1/2 carriers, possibly more so for premenopausal women." (PMID 31213659, 2019). "Mutations in BRCA1 result in predisposal to breast and ovarian cancers, but many variants exist with unknown clinical significance (VUS)." (PMID 31683985, 2019). "Furthermore, somatic mutations and epigenetic inactivation of BRCA1/2 have been implicated in sporadic ovarian cancer." (PMID 31109041, 2019). "Finally, we identified multiple point mutations in two genes that confer a significant increased risk for ovarian cancer, BRCA1 and MLH1, in patients with irregular menstruation." (PMID 30866919, 2019). "Mutations in the BRCA1 tumor suppressor gene (a component of homologous recombination repair) are associated with increased genomic stability and suggested to account for up to 10% of breast and ovarian cancers." (PMID 35582567, 2019). "BRCA1/2 mutation status could improve serum tumor markers performance in ovarian cancer discriminative models." (PMID 30972954, 2019). "Risk reducing salpingo-oophorectomy (RRSO) is the most effective strategy for preventing ovarian cancer (OC) in BRCA1/2 germline mutation carriers, reducing OC risk up to 96% RRSO is currently recommended to these women after child bearing is complete, at age 35–40 (BRCA1) and 40–45 years (BRCA2)." (PMID 29881922, 2019). "Their efficacy in the treatment of several different types of cancers is currently being tested in a large number of clinical trials, but their current indication is as fourth line therapy of primarily ovarian cancers in patients with BRCA1/2 mutations who have responded to platinum treatment." (PMID 31329989, 2019). "F79 treatment resulted in synthetic lethality in BRCA1/2-mutated breast, pancreatic, and ovarian cancer cells and displayed synergistic effect with approved drugs such as imatinib (approved for BCR-ABL1-positive leukemia) and ATRA (for PML-RAR-positive leukemia)." (PMID 31615159, 2019). "BRCA1/2‐mutated ovarian cancers harbouring secondary mutations and exhibiting progression following platinum treatment may be resistant to both platinum and PARP inhibitors." (PMID 30672100, 2019). "The BRCA1/2 mutation prevalence is higher in young patients, patients with first-degree relatives with breast or ovarian carcinomas, patients with triple-negative carcinomas, patients with bilateral carcinomas, patients with concomitant breast and ovarian carcinomas, and high genetic risk patients." (PMID 30713775, 2019). "The BRCAPRO model predicts the probability of carrying a BRCA1 or BRCA2 mutation, as determined by the status of breast and ovarian cancer, as well as the ages, of the patient’s first and second-degree relatives, and is guided by the prevalence and penetrance of BRCA1 and BRCA2 mutation in carriers." (PMID 30832243, 2019).
ovarian carcinoma (continued). "Olaparib, rucaparib, niraparib, and talazoparib targeting PARP1/2 have been approved by the United States Food and Drug Administration (FDA) for the treatment of breast or ovarian cancer in patients harboring HR mutations that induce synthetic lethality in the BRCA1 or BRCA2 gene." (PMID 31795418, 2019). "The interim analysis of SOLO1 (NCT01844986) showed that BRCA1/2-mutated ovarian cancer patients could significantly benefit from Olaparib treatment (hazard ratio of cancer progression or patient death = 0.30, 95%CI 0.23–0.41, P < 0.001)." (PMID 31521196, 2019). "However, to date, PARP inhibitor treatment has been restricted to patients with BRCA1/2 mutation-associated breast and ovarian cancer." (PMID 30741937, 2019). "BRCA1/2 mutation detection could become a routine clinical practice for evaluation of women with ovarian cancer for personalized medicine." (PMID 30972954, 2019). "The present results highlight a novel relationship between BRCA1 and autophagy, which may provide insight into the etiology of BRCA1‐associated ovarian cancer, and improve our understanding of resistance mechanisms in ovarian cancer." (PMID 30636383, 2019). "Olaparib has been shown to sensitize cells to these treatments in cells that have deficiencies in some DNA repair mechanisms and, for this reason, it has been used in breast and ovarian cancer with BRCA1 mutations, or in mantle cell lymphomas with alterations of the ATM pathway." (PMID 31101118, 2019). "In fact, this class of agents has been clearly shown in preclinical studies to be extremely active in cellular systems deficient in HR repair by a synthetic lethality basis and such activity has been validated in clinical trials in BRCA1/2 mutation carriers with ovarian carcinomas." (PMID 30669514, 2019). "Here, we review genetic testing of high-penetrance hereditary breast and ovarian cancer genes, including BRCA1 and BRCA2, for the purpose of identifying high-risk individuals who would benefit from earlier screening and more sensitive methods such as magnetic resonance imaging." (PMID 30832243, 2019). "Defects in genes involved in HR DNA repair can sensitize cancer cells to poly(ADP-ribose) polymerase (PARP) inhibitors, a class of drugs already approved by the Food and Drug Administration (FDA) for breast and ovarian cancer carrying germline mutations in BRCA1/2 genes." (PMID 31242618, 2019). "The discovery of synthetic lethal interactions between poly (ADP-ribose) polymerase (PARP) inhibitors and BRCA genes, which are involved in homologous recombination, led to the approval of PARP inhibition as a monotherapy for patients with BRCA1/2-mutated breast or ovarian cancer." (PMID 31640753, 2019). "In addition, 50% of ovarian cancer patients present with dysfunctional BRCA1/2, however currently there is a shortage of BRCA-deficient models." (PMID 31117198, 2019). "Hence, prophylactic BSO in patients with BRCA1 or BRCA2 mutation has been shown to reduce ovarian cancer risk by 96%." (PMID 31915530, 2019). "The loss of BRCA2 and BRCA1 function is frequent in breast and ovarian cancers." (PMID 31632280, 2019). "Considering BRCA1 is well-known to be associated with ovarian cancer, we assumed that NUSAP1 could also be a promising biomarker for OC." (PMID 31729978, 2019). "Nearly half of all type II ovarian cancers are associated with BRCA1/2 gene mutations." (PMID 30362670, 2019). "Therapeutic efficacy of the combination was seen in a BRCA1-deficient ovarian cancer model." (PMID 31835379, 2019). "Similarly, in high-grade ovarian cancer altered BRCA1/2 results in a higher mutational load, therefore, tumors harbor more tumor-specific neoantigens, increased TILs including CD3+ and CD8+ and PD-1 and PD-L1 expression." (PMID 31658756, 2019). "Therefore, we estimated the age-specific cumulative risk of BRCA1/2-associated breast and ovarian cancer in Chinese women." (PMID 29861850, 2018).